ZNF451 (zinc finger protein 451)
Diseases named in the same sentence as ZNF451 in open-access papers:
ZNF451 is named in the same sentence as 24 diseases in open-access papers, as found by Europe PMC text mining. Sharing a sentence is not in itself a finding about the gene and the disease. The quoted sentences say what the papers report.
promyelocytic leukemia (2 papers, 2015 to 2017). "On the other hand, ZFP451 (zinc finger protein 451) is a promyelocytic leukemia nuclear body-associated transcriptional coregulator, and modulates transcription by regulating protein subnuclear localization." (PMID 28720711, 2017). "The main isoform of ZNF451 is a nuclear protein that, upon sumoylation, localizes to promyelocytic leukemia bodies and interacts with the androgen receptor." (PMID 25735770, 2015).
prostate carcinoma (2 papers, 2024). A carcinoma that arises from epithelial cells of the prostate gland. "For instance, ZNF451 positively regulates androgen signaling in prostate cancer cells by acting as a transcriptional coactivator for the androgen receptor." (PMID 38600524, 2024).
atrial fibrillation (1 paper, 2017). A disorder characterized by an electrocardiographic finding of a supraventricular arrhythmia characterized by the replacement of consistent P waves by rapid oscillations or fibrillatory waves that vary in size, shape and timing and are accompanied by an irregular ventricular response. "As a whole, our data imply that regulatory polymorphisms which alter expression levels of upstream regulators of this gene network (such as Nkx2-5, Mef2a, SRF, Nostrin, Znf451, and Ttn) might predispose to atrial fibrillation." (PMID 28720711, 2017).
Cerebral atrophy (1 paper, 2025). Atrophy (wasting, decrease in size of cells or tissue) affecting the cerebrum. "Duplications of ZNF451 and FXN (Case 23) suggest altered transcriptional regulation and DNA repair mechanisms underlying cerebral atrophy and dental anomalies." (PMID 40869915, 2025).
fibrosis (1 paper, 2024). the formation of excess fibrous connective tissue in an organ or tissue in a reparative or reactive process. "Given that lung fibroblasts act as the principal effector cells in PF progression, we examined the expression of ZNF451 in the lung fibroblasts of mice following BLM-induced fibrosis." (PMID 38600524, 2024).
gastritis (1 paper, 2025). Inflammation of the stomach. "Furthermore, in the gastric mucosa of the patients with H. pylori-infected gastritis, USP15, ZNF451, TGFB1, and CCNT were identified as participants in the TGF-β signaling pathway, while FYB, HLA-DRB1, ANKRD24, and TMEM35 were implicated in T lymphocyte differentiation and immune response processes." (PMID 41035878, 2025).
leukemia (1 paper, 2012). A malignant (clonal) hematologic disorder, involving hematopoietic stem cells and characterized by the presence of primitive or atypical myeloid or lymphoid cells in the bone marrow and the blood. "SP100 and ZNF451 are both components of promyelocytic leukemia (PML) bodies, which are implicated in interferon-induced antiviral defenses." (PMID 22291592, 2012).
lung diseases (1 paper, 2024). "Accordingly, genetically enhancing ZNF451 expression or neutralizing PDGFB with a PDGFB-neutralizing antibody may represent a novel therapeutic strategy for PF and other fibroproliferative lung diseases." (PMID 38600524, 2024).
neuroblastoma (1 paper, 2022). Neuroblastoma (NB) is the most common solid, extracranial childhood tumor. "Coherently, the chimeric RNA zinc finger protein 451 (ZNF451)-BAG cochaperone 2 (BAG2) fusion, highly expressed in neuroblastoma, generated a novel oncogenic protein with distinct protein–protein binding properties compared to wild-type BAG2." (PMID 35269953, 2022).
osteosarcoma (1 paper, 2024). A usually aggressive malignant bone-forming mesenchymal neoplasm, predominantly affecting adolescents and young adults. "Overexpression of ZNF451 in cisplatin-resistant osteosarcoma cell lines may be associated with enhanced tumor drug resistance." (PMID 39534688, 2024). "The prognostic significance of OS-SUMOs was using the GSE21257 osteosarcoma dataset, where ZNF451, a SUMOylation-related gene, emerged as a key predictor of patient survival." (PMID 39534688, 2024). "Considering these findings, our results suggest that ZNF451 silencing accelerates apoptosis in osteosarcoma cells and restricts their proliferation." (PMID 39534688, 2024). "Further comprehensive research is required to fully understand the effect of ZNF451 on osteosarcoma resistance." (PMID 39534688, 2024). "Elucidating the role of ZNF451 in osteolysis will shed light on the biological basis of bone destruction in osteosarcoma patients and offer new therapeutic targets for clinical intervention." (PMID 39534688, 2024). "Although we observed that ZNF451 inhibits apoptosis and promotes proliferation of osteosarcoma cells both in vitro and in vivo, the specific molecular pathways or signaling networks through which it induces resistance require further investigation." (PMID 39534688, 2024). "Future research should aim to elucidate the complex interactions between ZNF451 and osteosarcoma cells, providing deeper insights that will enable optimization of clinical treatment strategies." (PMID 39534688, 2024). "To investigate ZNF451’s function in osteosarcoma cells, we synthesized 3 targeted siRNAs against ZNF451, designated as si-ZNF451#1, si-ZNF451#2, and si-ZNF451#3, to examine ZNF451’s function in osteosarcoma cells." (PMID 39534688, 2024). "In this study, we found that ZNF451 reduced the sensitivity of parental osteosarcoma cell lines to cisplatin, thereby inhibiting apoptosis." (PMID 39534688, 2024). "In summary, these findings highlight the critical role of ZNF451 in promoting osteosarcoma progression and underscore its potential as a therapeutic target and biomarker for osteosarcoma." (PMID 39534688, 2024). "The integration of GO, KEGG, GSVA, and GSEA suggests that ZNF451 plays a complex and multifaceted role in osteosarcoma, influencing ribosomal function, protein synthesis, cell proliferation, apoptosis, EMT, and migration." (PMID 39534688, 2024). "To assess ZNF451’s impact on the osteosarcoma immune microenvironment, we employed CibersortX, a technique that leverages marker-specific scRNA data, to analyze immune cell composition in TARGET-OS." (PMID 39534688, 2024). "In vitro experiments also revealed that ZNF451 knockdown promoted EMT in drug-resistant osteosarcoma cell lines (n = 3)." (PMID 39534688, 2024). "Immunofluorescence staining showed that ZNF451 was predominantly localized in the cytoplasm of osteosarcoma cells." (PMID 39534688, 2024). "In contrast, ZNF451 knockout in cisplatin-resistant osteosarcoma cell lines significantly increased apoptosis." (PMID 39534688, 2024). "qRT-PCR consistently showed elevated ZNF451 mRNA levels in all osteosarcoma cell lines compared to hFOB cells, with notably higher levels in U2OS and MG63 cells (n = 3)." (PMID 39534688, 2024). "In both in vivo and in vitro analyses, we explored the effects of ZNF451 on osteosarcoma development and progression." (PMID 39534688, 2024). "In this study, we found that ZNF451 knockout significantly reduced N-cadherin expression and increased E-cadherin expression in resistant osteosarcoma cell lines, leading to enhanced cell adhesion." (PMID 39534688, 2024). "As further research continues to explore the function and mechanisms of ZNF451, this molecule is expected to play a significant role in the personalized treatment of osteosarcoma, offering new hope for improving patient outcomes." (PMID 39534688, 2024).
osteosarcoma (continued). "Collectively, these results reveal the key role of ZNF451 in regulating osteosarcoma cell sensitivity to chemotherapeutic drugs." (PMID 39534688, 2024). "Our study demonstrated that β-cryptoxanthin significantly reduced the expression level of ZNF451, thereby inhibiting the malignant phenotype of cisplatin-resistant osteosarcoma cells." (PMID 39534688, 2024). "Our findings revealed that ZNF451 is overexpressed in osteosarcoma cell lines, with an even more pronounced increase in cisplatin-resistant variants." (PMID 39534688, 2024). "Through an in-depth analysis of osteosarcoma samples using single-cell data, we identified dysregulation or functional abnormalities of the SUMOylation-related gene ZNF451, which correlated positively to the recurrence and prognosis of osteosarcoma." (PMID 39534688, 2024). "Collectively, these pathways suggest the critical involvement of ZNF451 in the evolution, progression, and therapeutic response in osteosarcoma." (PMID 39534688, 2024). "In our study of ZNF451’s role in osteosarcoma, a variety of osteosarcoma cell lines (U2OS, Saos-2, MG63, 143 B, MNNG, and SJSA-1) and normal osteoblasts (hFOB) were selected for mRNA expression analysis." (PMID 39534688, 2024). "Molecular docking studies revealed a notable affinity between ZNF451 and primary osteosarcoma treatment drugs." (PMID 39534688, 2024). "By analyzing multiple single-cell and bulk RNA-sequencing datasets, we discovered that the SUMOylation-related gene ZNF451 promotes osteosarcoma recurrence and alters its immune microenvironment." (PMID 39534688, 2024). "Concurrently, β-cryptoxanthin may inhibit the malignant phenotype of cisplatin-resistant osteosarcoma cells by down-regulating ZNF451 expression." (PMID 39534688, 2024). "Additionally, β-cryptoxanthin has been identified as a potential therapeutic agent that inhibits osteosarcoma progression by targeting ZNF451." (PMID 39534688, 2024). "ZNF451, a key molecule, shows great potential for clinical applications in osteosarcoma." (PMID 39534688, 2024). "Additionally, the proportion of each osteoblast subpopulation varied significantly across different disease types, with the ZNF451-high Osteoblastic1 subpopulation being scarce in normal tissues but significantly increased in osteosarcoma tissues." (PMID 39534688, 2024). "The expression dynamics of ZNF451 in osteosarcoma cells were extensively studied, stratifying cells into high and low ZNF451 expression categories based on their median expression levels, and disparities in gene expression are visually represented in a volcano plot." (PMID 39534688, 2024). "This study elucidates the critical role of ZNF451 in osteosarcoma cells." (PMID 39534688, 2024). "Targeting ZNF451 with β-cryptoxanthin may offer a novel therapeutic approach to overcome cisplatin resistance, bringing hope to patients with cisplatin-resistant osteosarcoma." (PMID 39534688, 2024). "Collectively, ZNF451 is hypothesized to be a critical regulator of the biological behavior of osteosarcoma, influencing tumor growth, cellular movement, invasion, and environmental stress responses." (PMID 39534688, 2024). "Our research also indicated that ZNF451 regulates CD8+ T cell function, leading to their exhaustion and transition to the CD8T.EXH state, thereby disrupting the immune balance in the osteosarcoma microenvironment." (PMID 39534688, 2024). "Second, while the study identified the critical role of ZNF451 in osteosarcoma progression and drug resistance, the precise mechanisms by which ZNF451 contributes to tumor resistance are not yet fully understood." (PMID 39534688, 2024). "Furthermore, we investigated whether ZNF451 overexpression enhanced cisplatin resistance in MG63 and U2OS osteosarcoma cells." (PMID 39534688, 2024).
pancreatic ductal adenocarcinoma (1 paper, 2024). An infiltrating adenocarcinoma that arises from the epithelial cells of the pancreas. "Previous studies have shown that ZNF451 inhibits apoptosis of human pancreatic ductal adenocarcinoma cells." (PMID 39534688, 2024).
pulmonary fibrosis (1 paper, 2024). Chronic progressive interstitial lung disorder characterized by the replacement of the lung tissue by connective tissue, leading to progressive dyspnea, respiratory failure, or right heart failure. "To further confirm the role of ZNF451 in the pathogenesis of pulmonary fibrosis, we instilled Znf451-overexpressing lentivirus into lung tissue 10 days after the last BLM challenge." (PMID 38600524, 2024). "The overexpression of ZNF451 markedly alleviated, while the loss of ZNF451 aggravated, BLM-induced pulmonary fibrosis." (PMID 38600524, 2024). "Consistently, overexpression of ZNF451 protected mice from BLM-induced pulmonary fibrosis." (PMID 38600524, 2024). "Our results support that strategies aimed at increasing ZNF451 expression in fibroblasts could be a viable therapy against pulmonary fibrosis in clinical settings." (PMID 38600524, 2024). "This study was designed to investigate the role of ZNF451 in the pathogenesis of lung fibrosis." (PMID 38600524, 2024). "However, ZNF451 overexpression protects mice from BLM-induced pulmonary fibrosis." (PMID 38600524, 2024). "The role of ZNF451 in the pathogenesis of pulmonary fibrosis is unknown." (PMID 38600524, 2024).
triple-negative breast carcinoma (1 paper, 2024). An invasive breast carcinoma which is negative for expression of estrogen receptor (ER), progesterone receptor (PR), and human epidermal growth factor receptor 2 (HER2). "For instance, ZNF451 interacts with SLUG, facilitating SLUG-mediated CCL5 transcription, thereby driving the development of triple-negative breast cancer." (PMID 39534688, 2024).
cancer (2 papers, 2022 to 2024). A tumor composed of atypical neoplastic, often pleomorphic cells that invade other tissues. "ZNF451 is also implicated in cancer and its expression levels are increased in breast cancer, HCC and pancreatic cancer." (PMID 35887358, 2022). "It has been recently described that ZNF451 mediates TWIST2 sumoylation, which promotes its stability and consequently the activation of EMT, associated with cancer metastasis." (PMID 35887358, 2022). "The results from GSEA on “Pathways in Cancer” revealed that ZNF451 may play a substantial role in numerous cancer-related pathways." (PMID 39534688, 2024). "By employing enrichment analysis methods such as GO, KEGG, GSVA, and GSEA, we found that the gene is enriched in multiple pathways related to cancer progression, suggesting that ZNF451 might play a crucial role in reshaping the tumor immune microenvironment and cancer development." (PMID 39534688, 2024).
tumor (2 papers, 2019 to 2024). "To validate the results of the bioinformatics analysis, we employed experimental methods to demonstrate that ZNF451 is highly expressed in exhausted CD8+ T cells within tumor tissues." (PMID 39534688, 2024). "Second, ZNF451 holds potential as a therapeutic target for reversing tumor cell resistance and enhancing the efficacy of chemotherapy." (PMID 39534688, 2024). "Multiple studies have shown that ZNF451 regulates protein stability through SUMOylation, thereby promoting tumor progression." (PMID 39534688, 2024). "ZNF451’s involvement in antigen processing and presentation suggests a role in tumor immune evasion, altering the immune landscape." (PMID 39534688, 2024). "ZNF451 likely participates in critical regulatory processes, including cell proliferation, apoptosis, cell cycle control, signal transduction, cell migration, and invasion, as well as in the dynamics of the tumor microenvironment." (PMID 39534688, 2024). "Moreover, ZNF451 plays a crucial role in promoting osteolysis, contributing to tumor progression through bone resorption." (PMID 39534688, 2024). "Previous studies have suggested that ZNF451-mediated TOP2cc repair pathway may help tumor cells adapt to treatment with TOP2 inhibitors during chemotherapy." (PMID 39534688, 2024). "Future research should explore the interaction between ZNF451 and other known resistance, anti-apoptotic, and proliferative mechanisms to clarify its exact role in the development of tumor resistance and progression, which will provide a theoretical basis for new therapeutic strategies." (PMID 39534688, 2024). "We developed an animal model to assess ZNF451’s influence on tumor development." (PMID 39534688, 2024). "H&E staining provided evidence of a reduced tumor growth rate in the sh-ZNF451 group (n = 3)." (PMID 39534688, 2024). "Specifically, ZNF451 may enhance cell proliferation via intracellular protein synthesis, and affect tumor cell mobility and invasiveness by regulating EMT." (PMID 39534688, 2024). "The KEGG enrichment analysis indicated that ZNF451 potentially affects ribosomal function, which may subsequently influence protein synthesis and tumor cell growth." (PMID 39534688, 2024). "Additionally, ZNF451’s response to viral attacks and low-oxygen environments may also reflect its adaptability to the tumor microenvironment." (PMID 39534688, 2024). "Tumor volume significantly increased in mice treated with sh-NC U2OS cells and decreased notably in mice treated with sh-ZNF451- U2OS (n = 3)." (PMID 39534688, 2024).
infection (1 paper, 2025). The state of being infected such as from the introduction of a foreign agent such as serum, vaccine, antigenic substance or organism. "ZNF451 exerts negative regulation of the transforming growth factor beta receptor signaling pathway; this gene was the most downregulated gene by Toxoplasma gondii‐infected cells 48 h after infection." (PMID 40909016, 2025).
ZNF451 also shares sentences with these, for which no sentence is quoted: breast carcinoma (1 paper); Charcot-Marie-Tooth disease (1); chronic myeloid leukemia (1); colorectal cancer (1); endocrine cancers (1); glioma (1); non-small cell lung carcinoma (1); pancreatic cancer (1).